IL10 (interleukin 10)
Diseases named in the same sentence as IL10 in open-access papers (continued):
Sharing a sentence is not in itself a finding about the gene and the disease.
fibrosis (67 papers, 2008 to 2025). the formation of excess fibrous connective tissue in an organ or tissue in a reparative or reactive process. "The IL-10 over expression in the lung of transgenic mice causes mucus metaplasia, tissue inflammation, and airway fibrosis." (PMID 35482242, 2022). "However, three of these genes (DHCR7, IFN‐g, IL‐10) had additional evidence of an association with cirrhosis or fibrosis." (PMID 29397014, 2018). "Therefore, it is understandable how FRB supplementation, which resulted in decreasing the level of Tnf-α and maintaining the levels of Il-10 and Il-22, might have prevented collagen deposition and lowered the risk of fibrosis." (PMID 34070845, 2021). "Plasma IL-10/IL-17A ratio and IL-10/IL-22 ratio significantly differed between F0 fibrosis vs. moderate (F2)." (PMID 40918132, 2025). "Inflammatory cytokine levels (e.g., IL-6, IL-8, IL-10, TNF-α, and IFN-γ) in the synovial fluid are not only increased, but also correlate with IPFP fibrosis and have been associated with poorer clinical outcomes (e.g., Lysholm score)." (PMID 38549837, 2024). "Regarding liver disease progression and despite sparse evidence, IL-10 seems to protect against fibrosis." (PMID 36674897, 2023). "Twenty-four haplotype combinations were generated from the four selected encoding genes (-627 IL10, -400 MTP, 1183 SOD2, and APOE) among Mild and Severe fibrosis groups." (PMID 33924242, 2021). "The same result was shown when levels of IL-10 in serum from individuals with different degrees of periportal fibrosis were analyzed." (PMID 33692784, 2021). "IL-9 and IL-10 levels were significantly higher in the PBMC supernatants stimulated with SEA in patients with fibrosis." (PMID 34970264, 2021). "The cytokine IL-10 seems to have an important protective role in the pathogenesis of periportal fibrosis." (PMID 33692784, 2021). "The low levels of IL-10 (both plasma and mRNA) observed in the groups with fibrosis (F2 and F3-F4) and with high inflammation (A2) strongly suggest that IL-10 helps control the formation of inflammation-induced fibrosis, consistent with a previous report." (PMID 33125400, 2020). "High intrahepatic IL10 mRNA expression in the F0-F1 fibrosis and A0 and A1 inflammatory activity stages indicates an association of this cytokine with viral persistence and an immunosuppressive role in the early stages of chronic hepatitis." (PMID 33125400, 2020). "Our results are consistent with a previous study demonstrating improved cardiac dysfunction and cardiac fibrosis in macrophage-specific IL-10 knockout mice." (PMID 33264286, 2020). "In this analysis, IL-10 differed significantly between females and males in the nonfibrotic group whereas IL-13 was high in males with fibrosis compared to females in the same group." (PMID 29610679, 2018). "This notion is supported by the fact that IL-10 is significantly elevated in the serum of burn injury patients who later develop HTSs and in the serum of animals and patients with fibrosis in the lung, intestine, and liver." (PMID 29458433, 2018). "Several studies inhibited IL-10 by genetic way, and found IL-10 depletion resulting in liver injury or fibrosis exacerbation." (PMID 28039485, 2017). "The study demonstrated that the M6P-IL10 compound retained the anti-inflammatory and antifibrotic action typical of IL10, the latter indicated by a reduction of collagen type I deposition in a CCl4-induced rat model of experimental fibrosis." (PMID 26941644, 2016). "Independent variables were age, sex, IL28B, −238 TNF-α and −592 IL-10 polymorphisms, HCV genotype, HCV-RNA levels, significant fibrosis or cirrhosis and CD4+ T cell count." (PMID 25013899, 2014). "De Toma and Dierssen53 described the elevation of chemokines, specifically CXCL10, which,through stimulation of monocytes and IL-10, recruits fibrocytes and aids in theactivation of macrophages, facilitating lung damage such as fibrosis and leadsto a more severe manifestation of the disease." (PMID 37610949, 2023).
fibrosis (continued). "H&E staining showed that many inflammatory cells and the balloon‐like hepatocytes could be observed in the liver tissues retrieved from the fibrosis model group, to a lesser extent in the Ad‐IL10 group, compared with that in the Ad‐IL10 + CMC group." (PMID 36176604, 2022). "The presence of drug-induced corneal epithelial damage might be a prognostic factor for glaucoma filtration surgery, with local application of IL-10 being a potential new approach to the control of subconjunctival fibrosis after such surgery." (PMID 34373467, 2021). "Our findings suggest that corneal epithelial cells may protect against subconjunctival fibrosis by maintaining IL-10 levels and preventing the MRTF-A-dependent transdifferentiation of HTFs into myofibroblasts." (PMID 34373467, 2021). "However, a decrease in hepatic IL-10 favors an increase in persistent inflammatory infiltrate, resulting in severe fibrosis and cirrhosis." (PMID 33125400, 2020). "In addition, the same authors also reported an increase of IL-10 levels in BAL from trained mice group with fibrosis." (PMID 33123311, 2020). "However, IL-10 mRNA showed a different change trend, with a marked increase in the fibrosis+MSC group compared with the fibrosis group." (PMID 30635047, 2019). "It was also shown that overexpression of IL-10 aggravates silica-induced pulmonary inflammation and fibrosis in mice, which might relate to the promotion of Th2-type cytokine reaction and increased expression of IL-4 and IL-13." (PMID 29673394, 2018). "Similarly, in our studies, we have shown that IL-6 and IL-10 were increased in patients with fibrosis, together with STAT4 and STAT6." (PMID 30205811, 2018). "As we also determined interleukin 10 in the lavage to be associated with reduced fibrosis the serum and lavage do not appear to be reflecting the same process." (PMID 25889053, 2015). "Before DAA treatment, severe fibrosis or cirrhosis (F3/4) was associated with higher values of tumor necrosis factor-alpha (TNF-α) and genotypes transforming growth factor-beta-509 C/T_CC (TGF-β-509 C/T_CC), interleukine-10-1082 T/C_CC (IL-10-1082 T/C_CC), and IL-10-592 G/T_GT." (PMID 36674897, 2023). "Improved anti-bacterial immune response upon inhibition of IFNAR signaling was associated with decreased levels of IL-10, strengthening the idea that IL-10 might mediate the downstream mechanism by which IFN-I exerts its immune suppressive function in fibrosis." (PMID 35087852, 2021). "In the control group, high intrahepatic IL10 mRNA expression showed a positive association with F0-F1 fibrosis, no inflammation, low concentrations of liver enzymes and a high viral load; conversely, low intrahepatic IL10 mRNA expression showed a negative association with fibrosis progression." (PMID 33125400, 2020). "Anthropometric data, lipid profile, glycemic markers, cytokines (IL-6, IL-10, TNF-α), liver stiffness, and non-invasive fibrosis indices were compared across groups using standard statistical testing." (PMID 41470883, 2025). "Second, in various animal fibrosis models, ketanserin was shown to decrease the levels of several cytokines such as TNF-α, IL-10, IL-1β, IL-8, and IL-633,35,36." (PMID 38228622, 2024). "Increased anti‐inflammatory cytokine IL‐10 and CXCL9 levels were observed, resulting in lower lung hydroxyproline content and Ashcroft fibrosis score." (PMID 39582275, 2024). "As expected, the expression of collagen I, α‐Sma, and Timp1 was most profoundly down‐regulated in the Ad‐IL10 + CMC group, compared with that in the fibrosis model group and the Ad‐IL10 group." (PMID 36176604, 2022). "Despite the fibrosis group having presented a higher expression of pro-fibrotic molecules compared to WF/IFNE patients, it seems there is a regulation through IL-10 and T reg cells that is able to maintain the low morbidity of this group." (PMID 33692784, 2021). "There was no impact of liver steatosis on IL-4, IL-5, IL-10 and IL-22 levels in patients with mild fibrosis." (PMID 39200991, 2024).
fibrosis (continued). "Compared with BA patients without fibrosis, plasma levels of 3 anti-inflammatory cytokines including IL-4 (P = 0.026), IL-10 (P = 0.048), and IL-13 (P<0.001) were significantly increased in those with fibrosis." (PMID 35452452, 2022). "We observed a higher frequency of CD4+IL-10+ T cells in the PPF/PF group compared to individuals without fibrosis." (PMID 33692784, 2021). "Among pre-BS factors that may predict outcomes post-BS, those that have been found to be significant from the adipose tissue are VAT/SAT fibrosis, circulating CRP, Cd11b and IL10 adipose tissue mRNA levels, and possibly circulating leptin." (PMID 33670215, 2021). "Furthermore, those reduction were not related with a T-cell response switch in the liver since IL-10 expression did not change both in fibrosis and LXA4 treatment groups." (PMID 35307625, 2022). "Unlike the results found in a murine model, where IL-10 plays a key role in controlling the inflammatory response in fibrosis, in vitro studies evaluating the frequency of monocytes from individuals with different degrees of periportal fibrosis do not show an increase in IL-10 production." (PMID 33692784, 2021). "However, the IL-10/IL-13 ratio was higher in the group without fibrosis, compared to the PPF/PF group (p <0.01)." (PMID 33692784, 2021). "However, additional immune-related GO terms, such as MHC-I antigen presentation, interferon signaling, and hepatic fibrosis, were also enriched among up-regulated genes of Il10−/− mice but not in WT after radiation exposure." (PMID 31046668, 2019). "Furthermore, we investigated the link between the severity of the inflammation and the lack of IL-10 on the development of fibrosis using the heterotopic transplantation model." (PMID 30315190, 2018). "HCV patients without fibrosis and without necroinflammation had lower plasma and intrahepatic levels of IL-10 protein and mRNA than controls, suggesting that this profile may be related to the absence of viral clearance, which is characteristic of chronic infection by HCV." (PMID 33125400, 2020). "During CHC treatment, patients with SLD had distinct cytokine and growth factor kinetics, with SLD being the main source of variation in several cytokines (IL-5, IL-9, IL-10, IL-13, IL-17A, IL-22) and growth factors (EGF, VEGF and ANG), and it seems this was independent of fibrosis stage." (PMID 39200991, 2024). "Complementary to this, we analyzed the levels of IL-17 and IL-10 in non-stimulated and stimulated with SWAP or SEA PBMC supernatants according to different genotypes for the SNPs studied in each group of patients separately (no fibrosis and advanced fibrosis)." (PMID 34970264, 2021). "The SNPs in IL17A (rs2275913), IL10 (rs1800871 and rs1800872), and CD209 (rs2287886 and rs4804803) genes were genotyped in the no fibrosis patients (classified as Niamey 1) (n = 28) and fibrosis patients (classified as Niamey 7) (n = 9)." (PMID 34970264, 2021). "In this present study, IL-10 suppressed the formation of subretinal fibrosis, but this could be due to reduced CNV but not fibrosis per se." (PMID 24376495, 2013).
acute respiratory distress syndrome (66 papers, 2005 to 2026). Progressive and life-threatening pulmonary distress in the absence of an underlying pulmonary condition, usually following major trauma or surgery. "Elevated IL-10 levels promote bacterial expansion in the lung, thereby contributing to the development of malaria-associated acute respiratory distress syndrome (MA-ARDS)." (PMID 40520382, 2025). "Specifically, higher levels of IL-1β, IL-6, IL-8, IL-10, IL-18, and TNFα have been found in patients with severe disease and complications, such as acute respiratory distress syndrome (ARDS), which are the main cause of mortality in COVID-19." (PMID 40788382, 2025). "STC-1 secreted by human umbilical MSCs can promote the secretion of IL-10 in alveolar macrophages, thus alleviating the inflammatory storm caused by acute respiratory distress syndrome." (PMID 38693589, 2024). "Indeed, in a model of canine acute respiratory distress syndrome, mTH was also associated with a preserved kidney function and a reduction of plasma IL-10 level." (PMID 36012493, 2022). "For example, MSCs can suppress the inflammatory response by secreting HGF, IL-10, and TSG-6 in acute respiratory distress syndrome (ARDS) and COVID-19-associated pneumonia, thereby repairing the alveolar structure and reducing pulmonary edema." (PMID 39949625, 2025). "Given that increases in IL‐27 have been correlated with inflammatory reactivity and disease severity in acute lung injury/acute respiratory distress syndrome, the feedback regulation provided by IL‐10 likely contributes to its therapeutic effects." (PMID 39980189, 2025). "Increased proinflammatory cytokines such as IL-1, IL-2, IL-6, IL-7, IL-10, are frequently observed in many COVID-19 patients, which is closely related to the acute respiratory distress syndrome (ARDS), multiorgan failure and other severe symptoms." (PMID 37228604, 2023). "Immune activation and CRS were evidenced by a rapid increase in serum cytokines (IL-6, TNFα, IL-8, IL-10), acute respiratory insufficiency, and progressive acute respiratory distress syndrome." (PMID 35692034, 2022). "In CRS, infusion of cytotoxic T-cells leads to a rampant release of cytokines like IFN-γ, GM-CSF, TNF, IL-10, and IL-6, triggering an inflammatory response characterized by tachycardia, risk for acute respiratory distress syndrome (ARDS) acute hypoxic respiratory failure, and multiorgan failure." (PMID 34512641, 2021). "IL-10 UC-MSCs similarly enhanced human macrophage function, illustrating their therapeutic potential for infection-induced acute respiratory distress syndrome (ARDS)." (PMID 31200579, 2019). "Significant associations between the presence of IL-10-1082 G/G polymorphism and lower incidence and mortality rate of diseases were found in patients who suffered from acute respiratory distress syndrome (ARDS) which was similar to our findings." (PMID 28298812, 2017). "Of note, inadequate IL-10 responses were correlated with poor outcome in systemic inflammation and adult respiratory distress syndrome." (PMID 29234642, 2017). "Pro-inflammatory interleukins like IL-1β, IL-6, IL-2, IL-17 and IL-18 are critically involved in cytokine storm, hyperinflammation, and acute respiratory distress syndrome, whereas anti-inflammatory cytokines like IL-10 contribute to immune regulation and resolution of inflammation." (PMID 41683812, 2026). "Another negative correlation was observed between Spike S1+ EVs and immunosuppressive IL‐10, suggesting patients with higher Spike S1+ EVs are less prone to severe complications such as acute respiratory distress syndrome and secondary hemophagocytic lymphohistiocytosis." (PMID 35574251, 2022). "Similarly, specific cytokines such as IL-6, IL-8, and IL-10 have all been found at higher levels in blood derived from SARS-CoV-2-infected patients who experienced acute respiratory distress syndrome (ARDS)." (PMID 36865568, 2022).
acute respiratory distress syndrome (continued). "Furthermore, other research has also shown that lnc‐KCNQ1OT1 is able to negatively regulate IL‐6, TNF‐α, and IL‐10 expression in acute respiratory distress syndrome." (PMID 34761437, 2021). "In addition, Gong and colleagues further reported that the high IL-10-producing -1082 GG genotype was protective against organ failure and mortality in acute respiratory distress syndrome." (PMID 19939284, 2009). "For instance, in acute respiratory distress syndrome (ARDS), activated neutrophils release exosomes containing IL-10, polarizing macrophages into the M2c subtype, thereby inducing tissue remodeling and fibrosis after ALI." (PMID 38655063, 2024). "In studies of acute respiratory distress syndrome (ARDS), EVs carrying IL-4 and IL-10 payloads reduced inflammation by decreasing pro-inflammatory cytokines such as IL-1 beta and TNF alpha while increasing anti-inflammatory metabolites." (PMID 40428144, 2025). "In addition, increased secretion of IL-10 by transduction of MSCs with the MIG retroviral vector (MSCV-IRES-GFP) or transfection of IL-10 mRNA increases their anti-inflammatory effect in a model of acute graft-versus-host disease or acute respiratory distress syndrome." (PMID 38031182, 2023). "This cytokine storm is characterized by elevated plasma concentrations of IL-2, IL-7, IL-10, GCSF, IP-10, MCP-1, MIP-1A and TNF-α, and contributes to the development of acute respiratory distress syndrome (ARDS)." (PMID 34208037, 2021). "Massive systemic release of pro-inflammatory mediators such as interleukin (IL)-1β, IL-2, IL-6, IL-7, IL-10, tumor necrosis factor-α (TNFα), granulocyte colony-stimulating factor (G-CSF), etc., also known as cytokine storm, contributes to the acute respiratory distress syndrome (ARDS)." (PMID 35888733, 2022). "Elevated early pro-inflammatory cytokines like interleukins (IL2, IL6, and IL10) and Tumor necrosis factor (TNF) in ICU subjects reflect the cytokine storm leading to acute respiratory distress syndrome (ARDS) and progressive multiple organ failure." (PMID 33869282, 2021). "Finally, we replaced the reporter gene eGFP with IL10 as an exemplary anti-inflammatory cytokine and transplanted the IL10-MSCs into an LPS-induced acute lung injury (ALI) and acute respiratory distress syndrome (ARDS) mouse model." (PMID 37742038, 2023). "A recent study demonstrated that the raised levels of IL-6 and IL-10 were related with a high mortality in CAP, especially in severe CAP which could potentially increase the incidences of sepsis, lung injury and acute respiratory distress syndrome (ARDS)." (PMID 27846240, 2016). "For example, low IL‐10/TNF‐α ratios, rather than absolute plasma TNF‐α or IL‐10 concentrations, best correlated with adverse outcomes in patients with acute respiratory distress syndrome (ARDS)." (PMID 32940965, 2020).